FAN1 (FANCD2 and FANCI associated nuclease 1)
Description:
Nuclease required for the repair of DNA interstrand cross-links (ICL) recruited at sites of DNA damage by monoubiquitinated FANCD2. Specifically involved in repair of ICL-induced DNA breaks by being required for efficient homologous recombination, probably in the resolution of homologous recombination intermediates. Not involved in DNA double-strand breaks resection. Acts as a 5'-3' exonuclease that anchors at a cut end of DNA and cleaves DNA successively at every third nucleotide, allowing to excise an ICL from one strand through flanking incisions. Probably keeps excising with 3'-flap annealing until it reaches and unhooks the ICL. Acts at sites that have a 5'-terminal phosphate anchor at a nick or a 1- or 2-nucleotide flap and is augmented by a 3' flap. Also has endonuclease activity toward 5'-flaps.
Synonyms: hFAN1; KIAA1018; MTMR15; KMIN
Tractability: PROTAC: UniProt records ubiquitination sites on it; ubiquitination databases record sites on it.
Gene: Protein-coding gene on chromosome 15 (30,890,559 to 30,946,209, forward strand). Ensembl gene ENSG00000198690.
Subcellular location: Nucleus
Subcellular location (Human Protein Atlas): Cytosol; Nucleoplasm; Cytokinetic bridge; Primary cilium
Pathways (Reactome):
DNA Repair: Fanconi Anemia Pathway
Gene Ontology:
Molecular function: 5'-3' exonuclease activity; 5'-flap endonuclease activity; flap-structured DNA binding; phosphodiesterase I activity; protein binding; ubiquitin-modified protein reader activity; magnesium ion binding; DNA binding; hydrolase activity, acting on ester bonds; nuclease activity; nucleic acid binding
Biological process: DNA repair; double-strand break repair via homologous recombination; interstrand cross-link repair; nucleotide-excision repair
Cellular component: nucleoplasm; nucleus
Genetic constraint (gnomAD): Loss-of-function variants: 86 observed, 101.34 expected, observed/expected ratio (o/e) 0.85, 90% interval 0.71 to 1.01. The upper end of that interval is the gene's LOEUF score, 1.01, which puts it in group 4 of 6, group 1 being the genes least tolerant of losing a copy. Missense variants: 1,237 observed, 1,270.9 expected, observed/expected ratio (o/e) 0.97, 90% interval 0.93 to 1.02. Synonymous variants: 471 observed, 473.13 expected, observed/expected ratio (o/e) 1, 90% interval 0.92 to 1.07.
Gene-disease validity (ClinGen):
ClinGen rates the evidence that FAN1 causes each of these diseases.
karyomegalic interstitial nephritis (autosomal recessive): Definitive. Any interstitial nephritis in which the cause of the disease is a mutation in the FAN1 gene.
hereditary nonpolyposis colon cancer (autosomal dominant): Limited.
Homologues: Orthologues: chimpanzee FAN1 (99% identical), macaque FAN1 (95% identical), dog FAN1 (80% identical), pig FAN1 (76% identical), rabbit FAN1 (75% identical), mouse Fan1 (72% identical), guinea pig FAN1 (72% identical), rat Fan1 (71% identical), tropical clawed frog fan1 (51% identical), zebrafish fan1 (46% identical), Caenorhabditis elegans fan-1 (23% identical).
Diseases named in the same sentence as FAN1 in open-access papers:
FAN1 is named in the same sentence as 65 diseases in open-access papers, as found by Europe PMC text mining. Sharing a sentence is not in itself a finding about the gene and the disease. The quoted sentences say what the papers report.
Huntington disease (16 papers, 2019 to 2026). Huntington disease (HD) is a rare neurodegenerative disorder of the central nervous system characterized by unwanted choreatic movements, behavioral and psychiatric disturbances and dementia. "Patients with Huntington’s disease carrying the FAN1 R507H mutation have earlier than predicted onset of motoric symptoms." (PMID 40368883, 2025). "FAN1 is a DNA repair enzyme, and variants of FAN1 modify Huntington’s disease (HD) onset and progression." (PMID 37549289, 2023). "Genome-wide association studies of people with Huntington’s disease revealed a strong association between the FAN1 R507H mutation and early disease onset, however the underlying mechanism(s) remains unclear." (PMID 40368883, 2025). "However, FAN1 appears to play an antimutagenic role in triplet repeat expansion disease (TRD); the FAN1 locus on chromosome 15 was clearly identified by a genome-wide association study (GWAS) as a modifier of Huntington’s disease (HD)." (PMID 34228493, 2021). "A total of five Huntington’s disease modifier genes (FAN1, MLH1, MSH3, PMS2 and RRM2B) had OMIM phenotype entries, mainly for cancer-related diseases for DNA-repair-related genes." (PMID 39801710, 2025). "Re-analysis of Huntington’s disease AOO exome sequencing data showed that, in the early onset Huntington’s disease group, deleterious variants were enriched in FAN1 and depleted in LIG1, MSH3 and PMS1." (PMID 39801710, 2025). "Human genome-wide association studies have identified FAN1 and several DNA mismatch repair (MMR) genes as modifiers of Huntington’s disease age of onset." (PMID 37549289, 2023). "We next examined the relationship between cognitive function and five genetic polymorphisms linked to genes known to affect cognitive function in Huntington’s disease: MSH3, FAN1, MAPT, BDNF and COMT." (PMID 36519153, 2022). "In terms of genetic polymorphisms, we selected common polymorphisms that have been previously associated with cognitive function in Huntington’s disease [COMT, brain-derived neurotrophic factor (BDNF), FAN1, MSH3 and MAPT]." (PMID 36519153, 2022). "For this purpose, we analysed data from Track-HD, a multi-centre longitudinal study in Huntington’s disease gene carriers and focused on the role of intellectual enrichment (estimated at baseline) and the genes FAN1, MSH3, BDNF, COMT and MAPT in predicting cognitive decline and brain atrophy." (PMID 36519153, 2022). "FAN1 plays an important role in the removal of DNA interstrand crosslinks, and has been identified as a protective factor in the occurrence and progression of Huntington’s disease." (PMID 35053465, 2022). "FAN1 is also a modifier of Huntington's disease phenotypes in humans (Genetic Modifiers of Huntington's Disease (GeM-HD) Consortium 2019); thus, the modifiers found here could be common to other neurological diseases." (PMID 32317254, 2020). "Human FAN1 is a structure-specific endonuclease implicated in the repair of DNA interstrand crosslinks (ICLs) and the excision of extrahelical CAG repeats-whose pathological expansion underlies Huntington's disease (HD), a progressive and currently incurable neurodegenerative disorder." (PMID 41786746, 2026).
Fanconi anemia (14 papers, 2013 to 2025). Fanconi anemia (FA) is a hereditary DNA repair disorder characterized by progressive pancytopenia with bone marrow failure, variable congenital malformations and predisposition to develop hematological or solid tumors. "KIN is a rare hereditary condition linked to mutations in the FAN1 gene, which encodes an essential nuclease involved in the Fanconi anemia DNA damage response pathway." (PMID 40109725, 2025). "The name FAN1 (Fanconi anemia-associated nuclease 1) has been proposed because this protein interacts with Fanconi anemia pathway proteins." (PMID 39596669, 2024). "Variants in more than 20 genes, including FAN1, have been associated with Fanconi anemia." (PMID 39596669, 2024). "Perhaps even more surprising was the recent discovery that mutations in the Fanconi Anaemia and cancer-associated nuclease FAN1 could be causative for a subset of karyomegalic interstitial nephritis-type ciliopathies." (PMID 27335639, 2016). "Segui and collaborators performed Exome sequencing of three family members (Amsterdam I and MSS) and 176 other families with a history of CRC and concluded that the malfunctioning of Fanconi anaemia pathway (due to FAN1 alteration) might predispose patients to CRC13." (PMID 35181726, 2022). "When DNA inter-strand crosslinks occur, FAN1 is recruited to the lesion sites through an interaction between its ubiquitin-binding domain and the ubiquitylated complex of the Fanconi anemia pathway." (PMID 39596669, 2024). "As its name implies, FAN1 interacts with components of the Fanconi anemia group of proteins and there is little doubt that it participates in this pathway." (PMID 34228493, 2021). "FAN1 encodes Fanconi anemia-associated nuclease 1 (FAN1), which interacts with Fanconi Anemia Complementation group D2 (FANCD2) and Fanconi Anemia Complementation group I (FANCI), forming the Fanconi Anemia core complex." (PMID 34126972, 2021). "Although this may be a mechanism by which FAN1 mutations can give rise to ciliopathies, the underlying biology may be more complicated, especially given that phenotypes associated with karyomegalic interstitial nephritis-type ciliopathies are not evident in patients with Fanconi anaemia (FA)." (PMID 27335639, 2016). "That the FAN1 gene has not been found to be mutated in Fanconi anemia (FA) patients is most likely due to its functional redundancy with other nucleases in the pathway, such as SLX1 and/or SNM1A, neither of which is, like FAN1, encoded by an FA gene (see reference 25 for a recent review)." (PMID 34228493, 2021).
karyomegalic interstitial nephritis (14 papers, 2015 to 2024). "Pathogenic variants in the FAN1 gene lead to a systemic disease with karyomegalic interstitial nephritis (KIN) at the forefront clinically." (PMID 38892095, 2024). "Karyomegalic interstitial nephritis (KIN) is a genetic kidney disease caused by mutations in the FANCD2/FANCI-Associated Nuclease 1 (FAN1) gene on 15q13.3, which results in karyomegaly and fibrosis of kidney cells through the incomplete repair of DNA damage." (PMID 37759541, 2023). "FAN1 deficiency in humans results in karyomegalic interstitial nephritis, a rare inherited kidney disorder that results in renal failure, a pathology recapitulated in Fan1 knockout mice (52, 54, –56)." (PMID 37549289, 2023). "Our findings suggest that mitochondrial ROS are an important endogenous source of nuclear DNA damage in FAN1-deficient kidneys, which triggers the pathophysiology of karyomegalic interstitial nephritis." (PMID 37107275, 2023). "Kidney biopsies from patients with FAN1 mutations exhibit markedly enlarged nuclei in renal tubular epithelial cells and interstitial fibrosis, a pathologic condition known as karyomegalic interstitial nephritis (OMIM: 614817)." (PMID 37107275, 2023). "Fanconi anemia-associated nuclease 1 (FAN 1) mutation is a rare genetic mutation associated with karyomegalic interstitial nephritis (KIN) and various neurodevelopmental disorders." (PMID 39114219, 2024). "We present the case of a patient with chronic kidney disease due to a novel Fanconi anaemia-associated nuclease 1 (FAN1) mutation causing karyomegalic interstitial nephritis (KIN), and concurrent leukocyte chemotactic factor 2 amyloidosis (ALECT2)." (PMID 32111193, 2020). "Mutations in human Fan1 cause karyomegalic interstitial nephritis (KIN), but it is unclear whether defective ICL repair is responsible or whether Fan1 nuclease activity is relevant." (PMID 26980188, 2016). "Despite strong molecular evidence supporting its implication in ICL repair, mutation of FAN1 in humans does not lead to FA but causes karyomegalic interstitial nephritis (KIN) and increased susceptibility to colorectal cancer." (PMID 30257459, 2018). "Moreover, subsequent studies have demonstrated that mutations in FAN1 cause karyomegalic interstitial nephritis (KIN), implicating a vital role for FAN1 in kidney function and a correlation between DNA damage and chronic kidney failure." (PMID 25547363, 2015). "Moreover, the role of FAN1 in ICL repair does not require targeting by FANCD2, and mutation of FAN1 does not result in FA but is associated with karyomegalic interstitial nephritis, a chronic kidney disease." (PMID 35137093, 2022). "Although FANCD2-associated nuclease 1 (FAN1) contributes to ICL repair, FAN1 mutations predispose to karyomegalic interstitial nephritis (KIN) and cancer rather than to FA." (PMID 29051491, 2017).
chronic kidney disease (5 papers, 2020 to 2024). Impairment of the renal function secondary to chronic kidney damage persisting for three or more months. "In clinical practice, the FAN1 mutation-related disorder should be suspected in the presence of adulthood-onset chronic kidney disease of unknown origin, elevated liver enzymes, and recurrent infections, even without a family history." (PMID 38892095, 2024). "This is the first reported case of a patient homozygous/bi-allelic for FAN1 c.1899deletion causing KIN and the first time these two rare causes of chronic kidney disease have been described in the same patient, who unusually had no proteinuria." (PMID 32111193, 2020). "Genetic sequencing identified a novel FAN1 mutation as the cause of her KIN and she is being managed conservatively for chronic kidney disease." (PMID 32111193, 2020). "Additionally, FAN1 inactivation triggers chronic kidney disease in zebrafish via a similar mechanism." (PMID 32351541, 2020). "A diagnosis of KIN secondary to a novel homozygous single base pair deletion c.1899del in the FAN1 gene with concurrent ALECT2 was made, and the patient is currently being managed supportively for her chronic kidney disease." (PMID 32111193, 2020).
interstitial nephritis (5 papers, 2016 to 2025). Inflammation of the renal tubules and supporting tissues of the kidney. "In summary, we report here the high incidence of karyomegalic interstitial nephritis in French Polynesia owing to a recurrent FAN1 pathogenic variant with a founder effect that occurred more than 200 years ago." (PMID 34386670, 2021). "While FAN1 mutations are the most well-established genetic cause of KIN, other genetic variations, including UMOD, may contribute to a similar tubulointerstitial nephritis phenotype, potentially modifying disease expression." (PMID 40529986, 2025).
schizophrenia (4 papers, 2016 to 2020). A major psychotic disorder characterized by abnormalities in the perception or expression of reality. "An exome sequencing study identified a cluster of rare non-synonymous variants located within a 20-kb window that spans several functional domains of FAN1, which were associated with schizophrenia with depressive features, schizoaffective disorder and ASD." (PMID 26798408, 2016). "The FAN1 gene is located at 15q13.3, a region affected by multiple microdeletions that predispose to a number of clinical phenotypes, including schizophrenia, autism spectrum disorder (ASD), attention deficit hyperactivity disorder, epilepsy and intellectual disability." (PMID 26798408, 2016). "Furthermore, a pilot study of CNVs on the data set from a total of 3,414 patients with schizophrenia, 713 patients with bipolar disorder, and 3,215 controls, showed that CNVs affecting 15q13.2 (ARHGAP11B and FAN1 genes) appeared to be schizophrenia-specific." (PMID 33510659, 2020).
anaemia (3 papers, 2016 to 2024). "Variants in the Fanconi-anaemia pathway-associated protein FAN1 (MIM: 613534) strongly associated with altered AaO, and FAN1 has been convincingly shown to significantly alter repeat expansion in multiple models." (PMID 38749429, 2024).
autism (2 papers, 2020 to 2021). Persistent deficits in social interaction and communication and interaction as well as a markedly restricted repertoire of activity and interest as well as repetitive patterns of behavior. "In line A_333N, two mutations had very strong association scores as potential modifiers: A mutation in SH3 and multiple ankyrin repeat domains 1 (Shank1) was a strong candidate gene based on its autism associations, whereas a mutation in Fan1 would be consistent with the DDR pathway." (PMID 32317254, 2020). "We also identified PSGs associated with communication disorders, such as autism (CNTNAP4, AHI1, FAN1, SNTG2, and GRIP1) and dyslexia (KIAA0319)." (PMID 33441416, 2021). "Furthermore, the PSGs expressed in the brain and under the highest positive selection include CNTNAP4, FAN1, SNTG2, and KIAA0319, which also display high levels of expression in the cerebellum and have been associated with communication disorders, such as autism and dyslexia." (PMID 33441416, 2021).
chronic kidney failure (2 papers, 2015). "In addition, humans lacking the FAN1 nuclease develop chronic kidney failure with features similar to the Adh5−/−Fancd2−/− mice that we report here." (PMID 26412304, 2015).
ciliopathies (2 papers, 2016 to 2021). "Indeed, given the young age and small cohort of current ciliopathy patients with causative mutations in either FAN1 or MRE11, it is too early to determine if these patients have an increased risk of developing cancer." (PMID 27335639, 2016). "A number of proteins, such as fanconi-associated nuclease 1 (FAN1), origin recognition complex subunit 1 (ORC1), envelope glycoprotein gp160 (VCP) and ATM interactor (ATMIN), are DDR proteins that have been implicated in ciliopathies." (PMID 34828368, 2021).
colorectal cancer (2 papers, 2022 to 2025). A primary or metastatic malignant neoplasm that affects the colon or rectum. "Despite the arising evidence showing a possible relationship between FAN1 and colorectal cancer or even with FCCTX, we had not enough evidence to categorize the variants in any pathogenic class." (PMID 35181726, 2022).
encephalitis (2 papers, 2022 to 2024). An acute inflammatory process affecting the brain parenchyma. "Finally, CNVs on PRDM1 and CD274 were significantly linked to encephalitis, and CNVs on PRDM1, CD274, TSHR and FAN1 were significantly linked to myositis." (PMID 35053465, 2022). "Regarding CNVs, significant markers included PRDM1 deletions and IL1RN (IRAE), CD274 duplications and SLCO1B1 (hepatitis), PRDM1 and CD274 (encephalitis), and PRDM1, CD274, TSHR, and FAN1 (myositis)." (PMID 35053465, 2022). "Furthermore, the following genetic alterations were identified being associated with IRAE: SMAD3 (pancreatitis); CD274, SLCO1B1 (hepatitis); PRDM1, CD274 (encephalitis); PRDM1, CD274, TSHR, FAN1 (myositis)." (PMID 35053465, 2022).
fragile X syndrome (2 papers, 2019 to 2021). A genetic syndrome caused by mutations in the FMR1 gene which is responsible for the expression of the fragile X mental retardation 1 protein. "Inactivation of Fan1 induced somatic expansion of a CGG repeat in a mouse Fragile X syndrome model, indicating that the impact of FAN1 variation can extend to other non-CAG, non-coding repeat diseases." (PMID 31398342, 2019). "The FAN1 locus has also been linked to a second TRD, fragile X syndrome." (PMID 34228493, 2021).
Hepatitis (2 papers, 2022 to 2024). Inflammation of the liver. "CNVs on IKZF1, FAN1 and IL1RN were linked to IRAE, colitis, hepatitis or pancreatitis." (PMID 35053465, 2022).
hypophysitis (2 papers, 2023 to 2025). Inflammation of the pituitary gland. "A study analyzing 95 melanoma patients treated with ICIs found that genes affected by VARs associated with hypophysitis include SMAD3, PRDM1, and IL1RN, while genes affected by CNVs related to the occurrence of hypophysitis are TERT, SMAD3, JAK2, PRDM1, FAN1, CD274, and UNG." (PMID 37623461, 2023).
melanoma (2 papers, 2020 to 2025). A malignant, usually aggressive tumor composed of atypical, neoplastic melanocytes. "FAN1 was the most common germline mutation gene in our cohort, of which 27 variations were found, followed by the genes EGFR, ERBB2, and MSH3, which were found mutated 20 times in melanomas of our study." (PMID 32083130, 2020).
myositis (2 papers, 2022 to 2024). "CNVs on TSHR and FAN1 were significantly linked to myositis (p = 0.049 and p = 0.039)." (PMID 35053465, 2022).
renal failure (2 papers, 2023). "Importantly, administration of JP4-039 for the first two weeks after the initiation of cisplatin treatment attenuated cisplatin-induced renal failure in FAN1-null mice." (PMID 37107275, 2023).